LBH (LBH regulator of Wnt signaling pathway)
Description:
Transcriptional activator which may act in mitogen-activated protein kinase signaling pathway.
Tractability: PROTAC: its protein half-life has been measured.
Gene: Protein-coding gene on chromosome 2 (30,231,534 to 30,323,730, forward strand). Ensembl gene ENSG00000213626.
Subcellular location: Nucleus; Cytoplasm
Subcellular location (Human Protein Atlas): Vesicles
Gene Ontology:
Molecular function: protein binding
Biological process: negative regulation of DNA-templated transcription; positive regulation of DNA-templated transcription; regulation of MAPK cascade; mammary gland development; mammary gland epithelial cell differentiation; negative regulation of intracellular estrogen receptor signaling pathway; negative regulation of stem cell differentiation; positive regulation of mammary stem cell proliferation; positive regulation of somatic stem cell division; positive regulation of somatic stem cell population maintenance; regulation of DNA-templated transcription; regulation of gene expression
Cellular component: cytoplasm; nucleus; protein-containing complex
Genetic constraint (gnomAD): Loss-of-function variants: 6 observed, 11.05 expected, observed/expected ratio (o/e) 0.54, 90% interval 0.3 to 1.07. The upper end of that interval is the gene's LOEUF score, 1.07, which puts it in group 4 of 6, group 1 being the genes least tolerant of losing a copy. Missense variants: 110 observed, 138.49 expected, observed/expected ratio (o/e) 0.79, 90% interval 0.68 to 0.93. Synonymous variants: 50 observed, 48.92 expected, observed/expected ratio (o/e) 1.02, 90% interval 0.81 to 1.29.
Homologues: Orthologues: macaque LBH (99% identical), chimpanzee LBH (93% identical), guinea pig LBH (93% identical), pig LBH (93% identical), mouse Lbh (90% identical), rabbit LBH (89% identical), dog LBH (87% identical), rat Lbh (86% identical), tropical clawed frog lbh (78% identical), zebrafish lbh (53% identical). Paralogues in human: LBHD1 (23% identical).
Diseases named in the same sentence as LBH in open-access papers:
LBH is named in the same sentence as 70 diseases in open-access papers, as found by Europe PMC text mining. Sharing a sentence is not in itself a finding about the gene and the disease. The quoted sentences say what the papers report.
breast carcinoma (8 papers, 2015 to 2023). "We previously reported that LBH overexpression in aggressive basal-like breast cancers is associated with WNT pathway genes." (PMID 37268816, 2023). "The Wnt pathway directly targets LBH in aggressive basal subtype breast cancers and epithelial development." (PMID 34739189, 2022). "Aside from being a key regulator in the Wnt/β-catenin pathway, LBH can regulate aspects of the cell cycle and is highly expressed in aggressive basal subtype breast cancers." (PMID 34370741, 2021). "In breast cancer, LBH is considered an oncogene directly regulated by the Wnt/ β-catenin pathway, and LBH overexpression leads to a more aggressive basal differentiation of breast cancer." (PMID 31119084, 2019). "LBH was found aberrantly overexpressed in MMTV-Wnt1 mammary tumors and in human basal breast cancers that display Wnt/β-catenin hyperactivation." (PMID 27420097, 2016). "The patterns of expression of LBH in normal mammary development and in human breast cancers are consistent with its role as a context-specific TGF-β target in primary tissues." (PMID 26686634, 2015). "Investigation of gene expression data from 1,980 primary breast cancers showed that LBH expression is highest in the Claudinlow subtype." (PMID 26686634, 2015). "We therefore sought evidence for a relevant role of LBH in both normal breast epithelium and in breast cancer." (PMID 26686634, 2015). "Namely, LEF1 is part of the Wnt/β-catenin signaling pathway, which includes for example genes such as c-Myc, LBH, Oct4, NANOG that have been associated with the upregulation of proteins typically involved in human breast cancer, gastrointestinal tumors, prostate cancer, leukemia, and others." (PMID 38003292, 2023). "However, LBH is overexpressed in worst prognosis basal-like breast cancers, the most aggressive and lethal tumor subtype, affecting 16% of breast cancer patients." (PMID 37268816, 2023). "Highly invasive, ER-negative basal human breast cancers show overexpression of the LBH gene." (PMID 34178034, 2021). "In addition, the transcription factor LBH was found to be a direct transcriptional target of Wnt/β-catenin signaling in breast cancer cells." (PMID 27420097, 2016). "Given that LBH is a direct WNT/β-catenin target gene in epithelial development and breast cancer, and has been shown to increase FAK-PI3K-AKT signaling in stomach cancer models, it is likely that LBH is involved in crosstalk between these two pathways." (PMID 37268816, 2023). "This is likely due to that LBH is not expressed in majority of hormone receptor-positive, luminal-type breast cancers, which account for 70–80% of breast cancers." (PMID 37268816, 2023).
rheumatoid arthritis (8 papers, 2018 to 2025). A chronic, systemic autoimmune disorder characterized by inflammation in the synovial membranes and articular surfaces. "This was unexpected, as loss of LBH expression in the autoimmune disease, rheumatoid arthritis (RA), has been shown to involve DNA hypermethylation of an LBH-specific enhancer region that is associated with increased RA risk." (PMID 37268816, 2023). "From a previous GWAS, human LBH has been reported to be associated with autoimmune disease such as rheumatoid arthritis." (PMID 30006735, 2018). "As LBH has been shown to be associated with other inflammatory disorders such as autoimmune diseases, in particular, rheumatoid arthritis, it might play a valuable role in IS and PD." (PMID 30984102, 2019). "LBH is regarded as a pivotal regulator in embryonic development and was downregulated in several diseases such as rheumatoid arthritis, SLE, and nasopharyngeal carcinoma." (PMID 33553423, 2021). "A recent study showed that LBH is involved in synovial pathology of rheumatoid arthritis." (PMID 30006735, 2018).
autoimmune disease (6 papers, 2018 to 2025). A disorder resulting from loss of function or tissue destruction of an organ or multiple organs, arising from humoral or cellular immune responses of the individual to their own tissue constituents. "LBH and related variants are reportedly associated with autoimmune diseases such as SLE, RA, and celiac disease." (PMID 32719717, 2020). "It has been shown that the limb bud and heart development (LBH) gene is a key dysregulated gene in RA and other autoimmune diseases and there are some evidence showing LBH could modulate the cell cycle." (PMID 37940858, 2023).
nasopharyngeal carcinoma (6 papers, 2019 to 2023). A carcinoma arising from the nasopharyngeal epithelium. "Since then, LBH has received attention as a new tumor-associated gene, and its role in nasopharyngeal carcinoma, hepatocellular carcinoma, prostate cancer, and lung adenocarcinoma has been studied." (PMID 31119084, 2019). "Liu found that LBH inhibits the proliferation of CNE1 cells in nasopharyngeal carcinoma by causing G1/S phase arrest." (PMID 31119084, 2019). "LBH inhibits cellular migration, invasion and epithelial-mesenchymal transition in nasopharyngeal carcinoma via downregulating αB-crystallin expression." (PMID 37180146, 2023). "Collectively, this study explored the mechanisms by which exosome-derived LBH modulates the progression of nasopharyngeal carcinoma." (PMID 34975330, 2022). "In a study by Liu, overexpression of LBH was shown to lead to G1/S phase arrest in nasopharyngeal carcinoma and act as a transcriptional cofactor of NF-κB." (PMID 31119084, 2019). "Additionally, LBH proteins can be transported by nasopharyngeal carcinoma– (NPC–) derived exosomes in both paracrine and autocrine manners, modulating the progression of NPC." (PMID 36110098, 2022).
glioma (5 papers, 2020 to 2024). A benign or malignant brain and spinal cord tumor that arises from glial cells (astrocytes, oligodendrocytes, ependymal cells). "In conclusion, we have revealed that LBH contributed to glioma progression both in vitro and in vivo." (PMID 34739189, 2022). "We identified a novel function of LBH with respect to promoting glioma progression in vitro and in vivo." (PMID 34739189, 2022). "Meanwhile, BrdU incorporation assays demonstrated that proliferation of glioma cells was inhibited by LBH knockdown and promoted by LBH overexpression." (PMID 34739189, 2022). "In the present study, we found that the expression of LBH was elevated in glioma tissues, glioma samples from TCGA database and glioma cells." (PMID 34739189, 2022). "The expression of LBH was increased in glioma samples from The Cancer Genome Atlas database, and upregulation of LBH was observed to be correlated with the poor survival of glioma patients." (PMID 34739189, 2022). "Together, these data suggest that LBH promotes proliferation and inhibits cell cycle arrest and apoptosis in glioma cells." (PMID 34739189, 2022). "We also report that expression of LBH was elevated in clinical glioma tissues compared to adjacent normal tissues, and was also enhanced in glioma cell lines." (PMID 34739189, 2022). "Our findings provide new insights into the mechanism by which LBH promotes the development of glioma, improving our understanding of the correlation between LBH with cancer." (PMID 34739189, 2022). "Our findings provide new insights into the mechanism by which LBH promotes the development of glioma, improving our understanding of the correlation of LBH with cancer." (PMID 34739189, 2022). "In conclusion, our findings suggest that LBH contributes to glioma progression in vitro and in vivo." (PMID 34739189, 2022). "To assess the potential correlation of LBH with glioma progression, we analyzed the LBH expression in glioma samples from TCGA database." (PMID 34739189, 2022). "Transwell assays revealed that migration and invasion of glioma cells were significantly reduced by LBH depletion but enhanced by LBH overexpression." (PMID 34739189, 2022). "Among these genes, LBH promotes angiogenesis in glioma through VEGFA-mediated ERK signaling under hypoxic conditions." (PMID 34604236, 2021). "Next, we evaluated the role of LBH in the modulation of migration and invasion in the glioma cells." (PMID 34739189, 2022). "Together, these data imply that the abnormal expression of LBH may contribute to the glioma progression." (PMID 34739189, 2022). "This implies that the abnormally expressed LBH in glioma may be involved in the progression of glioma in clinical context, serving as a potential biomarker of glioma." (PMID 34739189, 2022). "Significantly, the levels of LBH were increased in glioma samples relative to normal samples." (PMID 34739189, 2022). "Immunohistochemical staining showed that LBH was positive in the glioma tissues of patients." (PMID 34739189, 2022). "Next, we determined the impact of LBH in the glioma development in vivo." (PMID 34739189, 2022). "Similarly, western blot analysis validated that the protein expression of LBH was upregulated in the clinical glioma tissues relative to adjacent normal tissues." (PMID 34739189, 2022). "We further explored the effect of LBH on the progression of glioma cells." (PMID 34739189, 2022). "In the present study, we were interested in the role LBH in the pathogenesis of glioma." (PMID 34739189, 2022). "In the present study, we revealed that LBH could enhance migration, invasion and proliferation and also attenuate apoptosis in glioma cells." (PMID 34739189, 2022). "Moreover, the survival analysis showed that the upregulation of LBH is closely correlated with the poor survival of glioma patients." (PMID 34739189, 2022). "Together, these results suggest that LBH is able to promote tumor growth of glioma in vivo." (PMID 34739189, 2022).
glioma (continued). "Hypoxia could accelerate malignant progression in glioma by promoting the expression of LBH." (PMID 37180146, 2023). "In addition, LBH increased the migration and invasion of glioma cells in vitro." (PMID 34739189, 2022). "Nevertheless, the role of LBH in the glioma progression remains unclear." (PMID 34739189, 2022). "Moreover, tumorigenicity analysis revealed that LBH could promote the tumor growth of glioma cells in vivo." (PMID 34739189, 2022). "Similarly, depletion of LBH increased, whereas overexpression of LBH decreased, wound proportion in the cells, suggesting that LBH promotes the migration and invasion of glioma cells in vitro." (PMID 34739189, 2022). "Moreover, LBH overexpression enhances angiogenesis by regulating the vascular endothelial growth factor A‐related extracellular signal‐regulated kinase pathway in human glioma under hypoxia conditions." (PMID 34739189, 2022). "Moreover, G0/G1 phase cells were enhanced, whereas S phase and G2/M phase cells were reduced, by depletion of LBH in the cells, although the overexpression of LBH showed a reversed effect, suggesting that LBH was able to inhibit cell cycle arrest at the G0/G1 phase in glioma cells." (PMID 34739189, 2022). "However, the expression status and biological function of LBH in glioma, especially the role of LBH in the modulation of glioma malignant progression, remain unclear." (PMID 34739189, 2022). "This study identified the MAGs of IDH wild-type glioma and the prognostic model was constructed by genes including GNS, LBH and SCARA3." (PMID 33198677, 2020). "Interestingly, both CQ and also LBH have been shown to cross the blood-brain barrier (BBB), increasing the interest in glioma treatment." (PMID 38803536, 2024). "First, we found that LBH was upregulated in glioma cells, including SHG44, U87 and U251 cells, compared to normal HBE cells." (PMID 34739189, 2022).
Alzheimer disease (3 papers, 2018 to 2023). A progressive, neurodegenerative disease characterized by loss of function and death of nerve cells in several areas of the brain leading to loss of cognitive function such as memory and language. "Researchers integrated Alzheimer’s disease-GWAS data and identified LBH as a pathogenic gene of amyloid β accumulation that is tightly linked to immune system." (PMID 32719717, 2020).
gastric cancer (3 papers, 2019 to 2023). A primary or metastatic malignant neoplasm involving the stomach. "Importantly, in colon, pancreatic, esophageal, and stomach cancer reduced LBH DNA methylation was significantly associated with increased LBH mRNA expression." (PMID 37268816, 2023). "Notably, in colon, pancreatic, esophageal, and stomach cancer DNA hypomethylation of CpG islands in the LBH locus was associated significantly with increased LBH mRNA expression, as validated in cell line models, and with poor patient survival." (PMID 37268816, 2023). "Collectively, these data demonstrate that a combined LBH-WNT-Integrin gene signature reliably stratifies colon, pancreatic, and stomach cancer patients into high- and low-risk groups for cancer survival." (PMID 37268816, 2023). "All 18 LBH DNA methylation sites showed significant correlation with disease prognosis in stomach cancer, while two, three, and five DNA methylation sites in LBH affected overall patient survival in colon, pancreatic, and esophageal cancer, respectively." (PMID 37268816, 2023). "Other studies have shown that LBH is co-expressed with the Focal Adhesion (FAK)/Integrin signaling pathway in gastric cancer, and can both positively and negatively regulate Integrin expression." (PMID 37268816, 2023). "Upregulated expression of LBH is correlated with poor prognosis and enhanced invasion and proliferation of gastric cancer cells as a result of upregulating integrin/focal adhesion kinase/Akt signaling." (PMID 34739189, 2022). "Prognostically significant LBH overexpression has also been reported in hepatocellular, gastric cancers, and glioma, where it promotes cell proliferation, invasion, angiogenesis, and tumor growth, in part through FAK/PI3K/AKT- and/or VEGF/ERK-dependent mechanisms." (PMID 37268816, 2023). "The role of LBH in various cancer types is still controversial, and its specific role and molecular mechanism in the oncogenesis of gastric cancer (GC) remains largely unexplored." (PMID 31119084, 2019).
glioblastoma (3 papers, 2021 to 2025). The most malignant astrocytic tumor (WHO grade IV). "We confirmed the overexpression of LBH in glioblastoma, stomach, and liver cancers, and its underexpression in lung cancer, consistent with previous reports, expanding prognostic and molecular insight into LBH dysregulation in these cancers." (PMID 37268816, 2023). "At the same time, several genes downregulated in NPRL2−/− cells are also known to be downregulated in lung cancer (FBLN2, LBH, AMPH-1), glioblastoma (ELAVL2), and liver cancer (IGFBP4)." (PMID 41469472, 2025). "Even in a cancer, as divergent as glioblastoma, WNT was second most enriched, indicating a high degree of correlation between LBH and WNT signaling activity in cancer." (PMID 37268816, 2023). "A prognostic model of glioblastoma was constructed based on SUMOylation regulator-related molecules (ATF7IP, CCNB1IP1, and LBH)." (PMID 33898460, 2021). "Finally, a prognostic model of glioblastoma was constructed based on SUMOylation regulator-related molecules (ATF7IP, CCNB1IP1, and LBH)." (PMID 33898460, 2021).
hepatocellular carcinoma (3 papers, 2019 to 2024). A malignant tumor that arises from hepatocytes. "LBH (+ 31.9-fold) has been reported as a potential marker for hepatocellular carcinoma, as its overexpression was associated with poor prognosis." (PMID 33515271, 2021). "Results from studies by Chen have confirmed that LBH predicted poor prognosis in hepatocellular carcinoma." (PMID 31119084, 2019).
liver cancer (3 papers, 2022 to 2025). An epithelial or non-epithelial malignant neoplasm that arises from the liver. "LBH elevation is correlated with the poor prognosis of liver cancer patients." (PMID 34739189, 2022).
lung adenocarcinoma (3 papers, 2019 to 2024). A carcinoma that arises from the lung and is characterized by the presence of malignant glandular epithelial cells. "In contrast, LBH was most prevalently downregulated in lung adenocarcinoma (LUAD, −2.3 to −2.5), and lung squamous cell carcinoma (LUSC, −2.4-fold), confirming published data." (PMID 37268816, 2023). "Moreover, our team found that LBH is downregulated and predicts better overall survival (OS) outcome in lung adenocarcinoma." (PMID 31119084, 2019).
lung carcinoma (3 papers, 2022 to 2025). "Contrarily, LBH is underexpressed, next to lung cancer, in melanoma, ovarian, uterine, and cervical cancers." (PMID 37268816, 2023). "In contrast, LBH has been shown to be downregulated in nasopharyngeal and lung cancer, and to exert tumor-suppressive, non-invasive effects, in part by inducing G1/S cell cycle arrest downstream of TGFß and attenuating NF-κB transcriptional activity." (PMID 37268816, 2023). "LBH inhibits lung cancer cell invasion and growth and prophesizes survival outcomes." (PMID 34739189, 2022).